METTL21A (methyltransferase 21A, HSPA lysine)
Description:
Protein-lysine methyltransferase that selectively trimethylates residues in heat shock protein 70 (HSP70) family members. Contributes to the in vivo trimethylation of Lys residues in HSPA1 and HSPA8. In vitro methylates 'Lys-561' in HSPA1, 'Lys-564' in HSPA2, 'Lys-585' in HSPA5, 'Lys-563' in HSPA6 and 'Lys-561' in HSPA8.
Synonyms: FAM119A; HCA557B; LOC151194; HSPA-KMT
Tractability: Small molecule: a structure with a bound ligand is known; a high-quality ligand is known. PROTAC: ubiquitination databases record sites on it.
Target class: Writer; Protein methyltransferase; Epigenetic regulator
Safety:
Unwanted effects reported when the protein is acted on. In parentheses: how it was acted on, where the effect was seen, and who reports it.
remission (source: ClinPGx)
suicidal ideation (source: ClinPGx)
Gene: Protein-coding gene on chromosome 2 (207,580,631 to 207,626,256, reverse strand). Ensembl gene ENSG00000144401.
Subcellular location: Cytoplasm
Subcellular location (Human Protein Atlas): Nucleoplasm; Cytosol
Pathways (Reactome):
Metabolism of proteins: Protein methylation
Gene Ontology:
Molecular function: ATPase binding; heat shock protein binding; Hsp70 protein binding; protein binding; protein methyltransferase activity; protein-lysine N-methyltransferase activity
Biological process: negative regulation of protein folding; regulation of protein folding
Cellular component: cytoplasm; protein-containing complex; cytosol; nucleoplasm
Genetic constraint (gnomAD): Loss-of-function variants: 18 observed, 18.68 expected, observed/expected ratio (o/e) 0.96, 90% interval 0.67 to 1.43. The upper end of that interval is the gene's LOEUF score, 1.43, which puts it in group 5 of 6, group 1 being the genes least tolerant of losing a copy. Missense variants: 244 observed, 246.1 expected, observed/expected ratio (o/e) 0.99, 90% interval 0.89 to 1.1. Synonymous variants: 83 observed, 94.45 expected, observed/expected ratio (o/e) 0.88, 90% interval 0.74 to 1.05.
Homologues: Orthologues: chimpanzee METTL21A (99% identical), macaque METTL21A (99% identical), dog METTL21A (92% identical), pig METTL21A (91% identical), rat Mettl21a (90% identical), mouse Mettl21a (89% identical), guinea pig METTL21A (86% identical), zebrafish mettl21a (60% identical), tropical clawed frog mettl21a (57% identical). Paralogues in human: EEF1AKMT3 (41% identical), METTL21EP (34% identical), VCPKMT (33% identical), METTL21C (30% identical), METTL23 (22% identical).
Diseases named in the same sentence as METTL21A in open-access papers:
METTL21A is named in the same sentence as 2 diseases in open-access papers, as found by Europe PMC text mining. Sharing a sentence is not in itself a finding about the gene and the disease. The quoted sentences say what the papers report.
tumor (3 papers, 2011 to 2024). "METTL21B and METTL22 displayed tumor suppressive functions without activating Src (as assessed by colony formation, migration, and invasion assays) when Flag-METTL21A and Myc-METTL22 were overexpressed." (PMID 39309445, 2024). "METTL21A plays a role in protein modification pathways, while ANG and VEGFA are essential for vascular endothelial cell function, with implications for conditions like ALS and tumor angiogenesis." (PMID 38681774, 2023).
METTL21A also shares sentences with these, for which no sentence is quoted: esophageal SCC (1 paper).